EIF3I (eukaryotic translation initiation factor 3 subunit I)
Description:
Component of the eukaryotic translation initiation factor 3 (eIF-3) complex, which is required for several steps in the initiation of protein synthesis. The eIF-3 complex associates with the 40S ribosome and facilitates the recruitment of eIF-1, eIF-1A, eIF-2:GTP:methionyl-tRNAi and eIF-5 to form the 43S pre-initiation complex (43S PIC). The eIF-3 complex stimulates mRNA recruitment to the 43S PIC and scanning of the mRNA for AUG recognition. The eIF-3 complex is also required for disassembly and recycling of post-termination ribosomal complexes and subsequently prevents premature joining of the 40S and 60S ribosomal subunits prior to initiation. The eIF-3 complex specifically targets and initiates translation of a subset of mRNAs involved in cell proliferation, including cell cycling, differentiation and apoptosis, and uses different modes of RNA stem-loop binding to exert either translational activation or repression.
Synonyms: TRIP-1; EIF3S2; TRIP1; eIF3-beta; eIF3-p36; PRO2242
Tractability: Small molecule: a structure with a bound ligand is known. PROTAC: UniProt records ubiquitination sites on it; ubiquitination databases record sites on it; its protein half-life has been measured.
Gene: Protein-coding gene on chromosome 1 (32,221,077 to 32,245,397, forward strand). Ensembl gene ENSG00000084623.
Subcellular location: Cytoplasm
Subcellular location (Human Protein Atlas): Cytosol
Pathways (Reactome):
Metabolism of proteins: Formation of a pool of free 40S subunits; Formation of the ternary complex, and subsequently, the 43S complex; GTP hydrolysis and joining of the 60S ribosomal subunit; L13a-mediated translational silencing of Ceruloplasmin expression; Ribosomal scanning and start codon recognition; Translation initiation complex formation
Gene Ontology:
Molecular function: protein binding; translation initiation factor activity; RNA binding
Biological process: translational initiation; cytoplasmic translational initiation; formation of cytoplasmic translation initiation complex
Cellular component: eukaryotic translation initiation factor 3 complex; extracellular exosome; cytosol; eukaryotic translation initiation factor 3 complex, eIF3m; cytoplasm; eukaryotic 43S preinitiation complex; eukaryotic 48S preinitiation complex; synapse
Genetic constraint (gnomAD): Loss-of-function variants: 19 observed, 42.38 expected, observed/expected ratio (o/e) 0.45, 90% interval 0.31 to 0.66. The upper end of that interval is the gene's LOEUF score, 0.66, which puts it in group 2 of 6, group 1 being the genes least tolerant of losing a copy. Missense variants: 275 observed, 435.66 expected, observed/expected ratio (o/e) 0.63, 90% interval 0.57 to 0.7. Synonymous variants: 165 observed, 157.41 expected, observed/expected ratio (o/e) 1.05, 90% interval 0.92 to 1.19.
Homologues: Orthologues: chimpanzee EIF3I (100% identical), macaque EIF3I (100% identical), rabbit EIF3I (100% identical), dog EIF3I (99% identical), guinea pig EIF3I (99% identical), mouse Eif3i (99% identical), rat Eif3i (99% identical), tropical clawed frog eif3i (90% identical), zebrafish eif3i (84% identical), Drosophila melanogaster eIF3i (61% identical).
Diseases named in the same sentence as EIF3I in open-access papers:
EIF3I is named in the same sentence as 25 diseases in open-access papers, as found by Europe PMC text mining. Sharing a sentence is not in itself a finding about the gene and the disease. The quoted sentences say what the papers report.
glioma (7 papers, 2019 to 2025). A benign or malignant brain and spinal cord tumor that arises from glial cells (astrocytes, oligodendrocytes, ependymal cells). "To investigate the association between the EIF3i expression and the clinicopathological features of gliomas, we further compared the expression of eIF3i in gliomas stratified by WHO grade and IDH status." (PMID 31171919, 2019). "As a bioinformatics study, the study only revealed the functions that were possibly associated with eIF3i expression and the definite functions of eIF3i in glioma are still needed to be further confirmed." (PMID 31171919, 2019). "In addition, TMZ significantly reduced the expression of 9 eIFs, including eIF3I and eIFH In a previous study, eIF3I and eIF4H were increased in gliomas and significantly associated with the overall survival of glioma patients." (PMID 37907716, 2023). "However, eIF3I and eIF4H were the only analyzed eIFs that were significantly associated with survival differences of glioma patients." (PMID 33807050, 2021). "In line with our previous study, we conclude that eIFs, especially eIF3I and eIF4H, are interesting candidates for future glioma therapy research." (PMID 37907716, 2023). "In conclusion, we identified eIF3I and eIF4H as the most promising targets for future therapy for glioma patients." (PMID 33807050, 2021). "In particular, the prognostic value of eIF3I gene expression in IDH1/2 mutant lower grade gliomas was shown." (PMID 33807050, 2021). "Recently, systematically profiling found that the expression of eIF3b, eIF3i, eIF3k, and eIF3m was increased with the glioma grade and poorer overall survival." (PMID 32565801, 2020). "To address the potential clinical implications of eIF3i in gliomas, we also investigated the prognostic value of eIF3i expression in total glioma, LGG and GBM through Kaplan–Meier curves." (PMID 31171919, 2019). "To insight the molecular relevance of eIF3i expression in gliomas, we also investigated the expression of eIF3i in gliomas with different molecular subtypes defined by the TCGA." (PMID 31171919, 2019). "Among eIF3i, eIF3k alone or in combination, the expression of eIF3i was the more robust in stratifying the survival of glioma in various pathological subgroups." (PMID 31171919, 2019). "We also compared the prognosis ability of eIF3i, eIF3k alone or in combination, and the results showed that the expression of eIF3i was the more robust in stratifying the survival of glioma in various pathological subgroups." (PMID 31171919, 2019). "The results indicated that the expression levels of eIF3a, eIF3b, eIF3i, eIF3k, eIF3l and eIF3m were significantly (P < 0.05) correlated to the OS of glioma patients in both datasets." (PMID 31171919, 2019). "The elevated expression of eIF3i was also correlated with pathological features of gliomas and was an independent prognostic factor eIF3i in IDH-mutant LGG." (PMID 31171919, 2019). "Based on above findings, we focused our investigation on the eIF3i in the grade and prognosis of gliomas." (PMID 31171919, 2019). "Our study reveals the expression alterations during glioma progression, and highlights the prognostic value of eIF3i in IDH-mutant LGG." (PMID 31171919, 2019). "We noticed that the elevated expression of eIF3i (located on chromosome 1p) and eIF3k (located on chromosome 19q) were significantly correlated with the increased malignancy of glioma." (PMID 31171919, 2019). "Considering the clinical implication of 1p/19q codeletion in gliomas, we also compared the prognosis ability of eIF3i, eIF3k alone or in combination in stratified gliomas from CGGA dataset." (PMID 31171919, 2019). "The results showed that the eIF3i had higher expression in the Classical and Mesenchymal gliomas in both CGGA and TCGA datasets." (PMID 31171919, 2019). "Patients with gliomas were divided into high-expression and low-expression groups by the median expression level of eIF3i in total gliomas, LGGs and GBMs, respectively." (PMID 31171919, 2019).
glioma (continued). "Based on this, we further investigated the prognostic value of eIF3i (located on chromosome 1p), eIF3k (located on chromosome 19q), and the combination of eIF3i and eIF3k in gliomas with specific molecular features." (PMID 31171919, 2019). "To get an overview of eIF3i expression in gliomas and normal brain tissues, we analyzed the expression of eIF3i expression in the GEPIA database." (PMID 31171919, 2019). "Furthermore, NF-κB signalling can also be activated by the m6A reader EIF3i, which can affect mRNA processing, translation, and TCR signalling and is associated with the malignancy of glioma." (PMID 40469294, 2025). "This supports the hypothesis that eIF3I and eIF4H are of interest for future research on the improvement of glioma therapy." (PMID 37907716, 2023). "Our work suggests eIF3I and eIF4H as potential targets for future glioma therapy." (PMID 33807050, 2021). "Based on these, we systemically investigated the prognostic values of eIF3i (located on chromosome 1p) and eIF3k (located on chromosome 19q) in stratified glioma and identified that the expression of eIF3i was closely correlated with the OS of patients in serval stratified glioma subgroups." (PMID 31171919, 2019). "However, our study not only revealed the clinical implications and potential functions of eIF3i in gliomas but also revealed the expression changes of all eIF3 subunits during glioma progression." (PMID 31171919, 2019). "Importantly, we noticed that the expression of both eIF3i (located on chromosome 1p) and eIF3k (Located on chromosome 19q) were positively correlated with the malignancy of gliomas." (PMID 31171919, 2019). "However, the OS of glioma patients only correlated for eIF3I with LGG and for eIF4H with GBM." (PMID 33807050, 2021). "Therefore, targeting of eIF3I and eIF4H might represent a prospective approach towards improvement of glioma therapy." (PMID 33807050, 2021). "However, short OS was only associated with high eIF3I gene expression in low grade gliomas, but not in GBM." (PMID 33807050, 2021). "Protein and mRNA expressions of eIF3B, eIF3I, eIF4A1, eIF4H, eIF5 and eIF6 were significantly increased in high grade gliomas compared to CCBT and partially in low grade gliomas." (PMID 33807050, 2021). "Here, we addressed the prognostic value of eIF3i in gliomas, especially in IDH-mutant gliomas through analyzing large samples." (PMID 31171919, 2019). "In the CGGA dataset, the expression of eIF3i was significantly increased along with the increasing WHO grades (both P < 0.0001), and the expression of eIF3i was also significantly (P < 0.0001) increased in IDH-wildtype gliomas." (PMID 31171919, 2019). "Regarding the eIF3 complex, significantly higher protein expression in gliomas compared to CCBT was detected for eIF3B (III: p < 0.05), eIF3D (I: p < 0.05; III: p < 0.05), eIF3H (III: p < 0.05), eIF3I (I: p < 0.05, III: p < 0.001, IV: p < 0.01) and eIF3M (III: p < 0.01)." (PMID 33807050, 2021). "In addition, the expression levels of YTHDF3 and hnRNPA2/B1 are elevated in gliomas, but they may not have as much independent clinical significance as the highly expressed eIF3i in LGG." (PMID 40469294, 2025). "Moreover, high expression of eIF3i could be used as an independent prognostic factor for poor prognosis in IDH-mutant LGG, which may be highly useful in the diagnosis and treatment of glioma." (PMID 40469294, 2025). "The results showed that the expression of eIF3i had the superior predictive efficiency compared with eIF3k expression, combined expression of eIF3i and eIF3k, WHO grade and subgroups of WHO 2016 for predicting survival of patients with 1p/19q non-codeletion glioma in the CGGA dataset." (PMID 31171919, 2019).
hepatocellular carcinoma (4 papers, 2015 to 2019). A malignant tumor that arises from hepatocytes. "Increased expression of eIF3i has been used as a theranostic marker for using Akt specific inhibitors in human hepatocellular carcinoma." (PMID 31171919, 2019). "Concretely, the I subunit of the eIF3 complex (eIF3i) was found to be overexpressed in different tumor types including colon adenocarcinoma and adenoma, head and neck squamous cell carcinomas, hepatocellular carcinoma, breast cancer, cervical cancer and metastatic melanoma." (PMID 31370342, 2019). "Overexpressed-eIF3I interacts with the activated form of oncogenic Akt1 via inhibition of PP2A phosphorylation in human hepatocellular carcinoma, whereas the protein REDD1 enhances PP2A-mediated dephosphorylation of Akt resulting in repression of mTORC1 signaling in 293T cells." (PMID 31605257, 2019). "Previous studies demonstrated that the overexpression of eIF3I interacted with and activated the oncogenic Akt1 by preventing the PP2A-mediated dephosphorylation of Akt-1 in human hepatocellular carcinoma." (PMID 31605257, 2019).
breast carcinoma (3 papers, 2019 to 2022). "Eukaryotic initiation factor 3 (EIF3) is involved in the initiation process of protein translation and overexpression of its subunit eukaryotic translation initiation factor 3 (EIF3I) has been observed in breast carcinoma." (PMID 33571282, 2021). "Here, we determined that there was not a significant difference in the comparison between the expression of EIF3H and NPI grades, and that up-regulated EIF3I was correlated with a better outcome for patients with breast cancer, which made their function remain controversial." (PMID 35040374, 2022).
adenoma (2 papers, 2019 to 2024). A neoplasm arising from the epithelium. "Additionally, the expression of both eIF3a and eIF3i but not eIF3b and eIF3g is also increased in benign adenoma polyps." (PMID 39413959, 2024).
astrocytoma (2 papers, 2019 to 2021). "We showed that the expression of eIF3B, eIF3I, eIF4A1, eIF4H and eIF6 was significantly increased in astrocytomas, in particular in GBM, for protein and mRNA levels." (PMID 33807050, 2021). "Besides the already known eIFs, we demonstrated significantly elevated protein levels of eIF3D, eIF3H, eIF3I, eIF3M, p-eIF4G, eIF4H, eIF5 and eIF6 in astrocytoma tissue compared to CCBT." (PMID 33807050, 2021). "In LGGs, though patients with IDH-wildtype astrocytoma in low-expression group had longer (P = 0.059) OS than that of high-expression group in the CGGA database, the expression of eIF3i cannot stratify the OS of patients in TCGA dataset (P = 0.533)." (PMID 31171919, 2019).
lung adenocarcinoma (2 papers, 2019 to 2021). A carcinoma that arises from the lung and is characterized by the presence of malignant glandular epithelial cells. "In this sense, previous results from our research group identified putative biomarkers of the HSP90 inhibition response in lung adenocarcinoma; these included eukaryotic translation initiation factor 3 subunit I (EIF3I) and transketolase, among others." (PMID 33802597, 2021). "eIF3i, HSC71, MHC class I antigen, transketolase, citrate synthase, Rab-37, MLH1 and AGR2 might be putative biomarkers in HSP90 inhibition response in lung adenocarcinoma." (PMID 31370342, 2019). "Therefore, the down-expression of eIF3i observed in HCC827 and H3122 cell lines after treatment with HSP90 inhibitors could be a good prognostic factor for this therapeutic strategy in lung adenocarcinoma." (PMID 31370342, 2019).
melanoma (2 papers, 2017 to 2024). A malignant, usually aggressive tumor composed of atypical, neoplastic melanocytes. "EIF3i shRNA treatment efficiently inhibited metastases of mouse melanoma." (PMID 28193911, 2017). "Upon eif3i shRNA treatment, eIF3i proteins, as well as CD31 proteins, were significantly reduced in melanoma metastasis." (PMID 28193911, 2017).
colon cancers (1 paper, 2024). "Correlation analysis revealed a significant positive association between eIF3a and eIF3i overexpression in human colon cancers." (PMID 39413959, 2024). "The finding that the increased expression of eIF3a and eIF3i strongly associates with each other in 19 of the 22 matched pairs of human tissues is consistent with the conclusion that both eIF3a and eIF3i may be regulated similarly in colon cancers." (PMID 39413959, 2024). "Of the eIF3(a:b:i:g) subcomplex, eIF3i has been shown to overexpress in human colon cancers." (PMID 39413959, 2024). "While the association analyses using these datasets from different experiments have limitations, the fact that they were from the same samples and showed strong correlation suggests that Wnt/β-catenin signaling may contribute to the upregulation of both eIF3a and eIF3i in human colon cancers." (PMID 39413959, 2024). "Thus, eIF3a and eIF3i in the eIF3(a:b:i:g) subcomplex may be related to colon cancer and are up-regulated together prior to the formation of malignant colon tumors." (PMID 39413959, 2024). "As subunits in the eIF3(a:b:i:g) subcomplex, only eIF3a and eIF3i, but not eIF3b and eIF3g, are overexpressed in human colon cancers compared with their matching normal tissues." (PMID 39413959, 2024).
lung carcinoma (1 paper, 2022). "Previous studies have not reported the role of eIF3i in lung cancer; the results of this study may remind that eIF3i serves as a potential biomarker for LUSC." (PMID 35433477, 2022).
oligodendroglioma (1 paper, 2019). A well-differentiated (WHO grade II), diffusely infiltrating neuroglial tumor, typically located in the cerebral hemispheres. "Both eIF3i and eIF3k had the highest expression in IDH-wildtype GBM, but had the lowest expression in IDH-mutant, 1p/19q codeletion, oligodendrogliomas." (PMID 31171919, 2019).
ovarian carcinoma (1 paper, 2025). A malignant neoplasm originating from the surface ovarian epithelium. "Increased levels of eIF3i expression have been connected with worse prognostic results in patients with ovarian cancer." (PMID 39891297, 2025). "Several hub genes, such as RPL11, RPS4X, EIF3I, and RPS14, have been previously linked to various cancers and were confirmed to play crucial roles in ovarian cancer through this study." (PMID 39891297, 2025).
prostate carcinoma (1 paper, 2020). A carcinoma that arises from epithelial cells of the prostate gland. "Therefore, EIF3I, EIF3D, and HNRNPA2B1 can form a prognostic signature for prostate cancer relapse." (PMID 33273988, 2020).
thyroid cancer (1 paper, 2020). "We then designed the convergent and divergent primers to amplify the linear EIF3I mRNA and hsa_circ_0011385 by using cDNA and gDNA extracted from thyroid cancer tissues." (PMID 32082079, 2020). "Results showed that hsa_circ_0011385 could only be amplified by divergent primers in cDNA of thyroid cancer tissues; EIF3I could be only amplified by convergent primers in cDNA and gDNA of thyroid cancer tissues, suggesting that hsa_circ_0011385 was indeed circular." (PMID 32082079, 2020).